BRD4 (bromodomain containing 4)
Diseases named in the same sentence as BRD4 in open-access papers (continued):
Sharing a sentence is not in itself a finding about the gene and the disease.
osteosarcoma (14 papers, 2014 to 2025). A usually aggressive malignant bone-forming mesenchymal neoplasm, predominantly affecting adolescents and young adults. "Functional restriction of bromodomain-containing protein 4 (BRD4) reduced the susceptibility to erastin-induced ferroptosis of osteosarcoma cells both in vitro and in vivo." (PMID 37993451, 2023). "Next, BRD4 function-loss models in osteosarcoma cell lines SaoS2 and U2-OS were conducted with shRNA or inhibitor (+)-JQ1 that targeting BRD4, and then cells were exposed to a culture medium containing erastin to induce ferroptosis." (PMID 37993451, 2023). "Among them, MLLT3, ATM/ATR, DDX10, CASP1 and BRD4 have been extensively studied and shown to be associated with pathogenesis or clinical outcomes in osteosarcoma." (PMID 37894336, 2023). "Overall, we found a BRD4-mediated pre-mACSL3 splicing influences erastin-induced ferroptosis by affecting arachidonic acid synthesis in osteosarcoma cells." (PMID 37993451, 2023). "Specifically, ACSL3 is generally scattered in the nucleus or cytoplasm in osteosarcoma cells, but when BRD4 is interfered, ACSL3 is more dispersed in the cytoplasm with a decrease in overall protein levels." (PMID 37993451, 2023). "Collectively, inhibiting BRD4 helps protect osteosarcoma cells from erastin-ferrop at both in vivo and in vitro levels." (PMID 37993451, 2023). "Subcutaneous tumor models of osteosarcoma cells in nude mice were then constructed to evaluate the effects of BRD4 inhibition on erastin-ferrop in vivo." (PMID 37993451, 2023). "Conversely, knocking down ACSL3 in osteosarcoma cells overexpressing BRD4 revealed that the accumulation of arachidonic acid and erastin-ferrop induced by BRD4 can be further attenuated by ACSL3 inhibition." (PMID 37993451, 2023). "105B potently degrades BET proteins in U2OS osteosarcoma cell lines (BRD4 DC50 = 0.130 nM, Dmax = 78%) and KYSE180 esophageal squamous cell carcinoma cell lines (DC50 = 40 nM, Dmax = 70%), but shows no degradation in non-cancerous, MAGEA11-deficient HEK293T cells." (PMID 41279184, 2025). "The PROTACs were initially screened in U2OS osteosarcoma cells due to their known sensitivity to BRD4 inhibition, degradation, and MAGEA11 expression, confirmed via western blot.25, 28, 29 The PROTACs were screened in a 24 hour, 4-point titration from 10 - 0.01 μM concentrations." (PMID 41279184, 2025). "BRD4 can regulate RUNX2 expression directly in osteosarcoma." (PMID 38063851, 2024). "We transfected human osteosarcoma U2OS cells with full-length, GFP-tagged BRD4 individually mutated to alanine or phenylalanine at these four BD1 locations as well as with BRD4 BD2 mutated at Asn-433 (which corresponds to Asn-140 in BD1) and with a double Asn-140/Asn-433 mutant." (PMID 24497639, 2014). "In osteosarcoma preclinical models, PROTACs that target BET family proteins, specifically BRD4, 3 and 2 synergise with chemotherapy, trigger apoptosis, cell cycle arrest and significantly reduce tumour volume." (PMID 40983796, 2025). "Further, BRD4 enrichment was observed on the RUNX2 gene, which drives essential genes from drug resistance in osteosarcoma cells." (PMID 38172984, 2024). "Further, the endogenous binding relationship between SRPK2 and BRD4 in osteosarcoma cells was verified and the main binding site was analyzed in the CTD domain of BRD4." (PMID 37993451, 2023). "In this study, we first determined the contribution of BRD4 and ACSL3 to erastin- induced ferroptosis in osteosarcoma cells, and then elucidated the effects and regulation mechanisms of BRD4 on pre-mACSL3 splicing and expression." (PMID 37993451, 2023). "This activation histone mark at the GP130 TSS was confirmed in 143B osteosarcoma cells by ChIP-PCR, while NHWD-870 abrogated the BRD4 enrichment at TSS site in a dose-dependent manner." (PMID 34168981, 2021).
osteosarcoma (continued). "FRAP assays with human osteosarcoma cells transfected with GFP-BRD4 and GFP-BRD4-NUT reveal accelerated fluorescence recovery in the presence of JQ1, indicating that JQ1 displaces BRD4 from nuclear chromatin and increases the levels of freely diffusing BRD4." (PMID 27827996, 2016). "Finally, 18 paired osteosarcoma tissues and normal osteogenic tissues were selected from the GEO database (cancerous tissue matched 1:1 with adjacent osteogenic tissue, GSE99671) to analyze the expression correlation between BRD4, SRPK2, SRSF2 and ACSL3." (PMID 37993451, 2023). "It shows that the expression of ACSL3 was not correlated with the expression of BRD4 and SRPK2, but positively correlated with SRSF2, which is consistent with our findings in 10 cancerous tissues surgically removed from patients with osteosarcoma." (PMID 37993451, 2023).
renal cell carcinoma (14 papers, 2017 to 2025). "In renal cell carcinoma, BRD4 expression levels are markedly upregulated, and pyroptosis-associated proteins are significantly reduced." (PMID 39616223, 2024). "In renal cell carcinoma, the BRD4 knockdown and JQ1 treatment suppressed the epithelial-to-mesenchymal transition (EMT) and tumor growth progression via caspase-1-dependent pyroptosis in vitro and in vivo." (PMID 38136175, 2023). "BRD4 is upregulated in the renal cell carcinoma (RCC) cell lines 786-O and ACHN but downregulates caspase-1." (PMID 34522213, 2021). "As evidenced by both pharmacological and genetic data presented, BRD4 is a VS-5584 resistance factor in renal cell carcinoma (RCC) cells." (PMID 35614940, 2022). "However, the correlation between BRD4 and pyroptosis in renal cell carcinoma (RCC) remains elusive." (PMID 32303673, 2020). "Bromodomain-containing protein 4 (BRD4) and PI3K-AKT are both important for renal cell carcinoma (RCC) development and progression." (PMID 29228703, 2017). "Concurrent inhibition of bromodomain-containing protein 4 (BRD4) and signal transductor and activator of transcription 3 (STAT3) could potentially be an effective strategy against renal cell carcinoma (RCC)." (PMID 40078291, 2025). "In addition, recent studies have shown that inhibition of BRD4 in RCC suppresses cell proliferation as well as epithelial–mesenchymal transition (EMT) progression and plays an anti-tumour role in renal cell carcinoma by activating the NF-κB-NLRP3-Caspase-1 signalling pathway." (PMID 36702978, 2023). "In renal cell carcinomas, inhibition of BRD4 by genetic knockdown or JQ1 prevents cell proliferation and EMT, and induces NF-κB-NLRP3-Caspase 1-dependent pyroptosis, providing evidence for BRD4 being a potential target and JQ1 as a therapeutic agent for renal cell carcinomas." (PMID 33343366, 2020). "However, the efficacy of BET inhibitors in renal cell carcinoma (RCC) was poorly evaluated, and it remained to be answered whether BRD4, as well as other BET family members, can serve as therapeutic targets for the treatment of RCC." (PMID 30385738, 2018). "However, whether BRD4, as well as other BET family members, may serve as therapeutic targets in renal cell carcinoma (RCC) remains unknown." (PMID 30385738, 2018).
Cornelia de Lange syndrome (13 papers, 2019 to 2025). A rare syndrome characterized by low birth weight, delayed growth, intellectual disabillity, behavioral problems, and a distinctive facial appearance (thin, arched eyebrows, low set ears, small teeth, and small nose). "Review of the literature on Cornelia de Lange syndrome caused by pathogenic variations in the BRD4 gene sequence." (PMID 41300558, 2025). "Intriguingly, BRD4 has been implicated in the neurodevelopmental disorder Cornelia de Lange Syndrome (CdLS), typically caused by mutations in the cohesion complex gene NIPBL." (PMID 38567724, 2024). "The total number of patients with BRD4-associated Cornelia de Lange syndrome is very small, which may limit our understanding of the phenotypic heterogeneity." (PMID 35887114, 2022). "They recognised a significant overlap with the CdLS phenotype, suggesting that BRD4 haploinsufficiency is the likely cause of an atypical form of CdLS referred to as Cornelia de Lange Syndrome 6 (CDLS6)." (PMID 41300558, 2025). "It has been reported that haploinsufficiency of BRD4 is associated with Cornelia de Lange syndrome (CdLS), a severe multisystem neurodevelopmental disorder presenting with HL as one of the clinical phenotypes." (PMID 33015071, 2020). "The most common cohesinopathy, Cornelia de Lange syndrome, is caused by dysfunction in a variety of cohesin subunits, such as NIPBL, SMC1A, SMC3, RAD21, BRD4, HDAC8, and ANKRD11." (PMID 40943870, 2025). "The histone acetyltransferase bromodomain-containing protein 4 (BRD4), implicated in nucleosome eviction, can interact with NIPBL, and its mutation underlies a syndrome that resembles the cohesinopathy Cornelia de Lange Syndrome." (PMID 34943967, 2021). "Variants in genes encoding various structural or functional components of the cohesin complex, including RAD21, SMC1A, SMC3, BRD4, STAG1/2, NIPBL, HDAC8, WAPL, ANKRD11 and in single individuals PDS5A and ESPL1, have been implicated in Cornelia de Lange Syndrome (CdLS)." (PMID 32193685, 2020). "Cornelia de Lange Syndrome (CdLS) is a genetically heterogeneous disorder predominantly caused by De Novo heterozygous pathogenic variants in NIPBL (80% of cases), with less frequent involvement of SMC1A (5%), HDAC8 (4%), SMC3 (1–2%), RAD21 (<1%), and BRD4 (<1%)." (PMID 40700109, 2025).
Sepsis (13 papers, 2018 to 2026). Sepsis is defined as life-threatening organ dysfunction caused by a dysregulated host response to infection. "BRD4 is thought to be involved in regulating gene transcription by chromatin targeting, and recent reports have linked BRD4 as a regulator of inflammation and immune response during sepsis." (PMID 38178237, 2024). "Sepsis significantly reduces BRD4 expression in monocytes/macrophages in both human patients and murine models, with decreased BRD4 levels correlating with disease severity." (PMID 42060684, 2026). "Our findings reveal that BRD4 downregulation in human sepsis predicts disease severity, presenting BRD4 as both a biomarker and a therapeutic target." (PMID 42060684, 2026). "We identify BRD4, an epigenetic regulator, as a crucial modulator of macrophage antimicrobial function and survival in sepsis." (PMID 42060684, 2026). "XIST inhibition was also described to mitigate sepsis-induced acute liver injury by suppressing Bromodomain-containing Protein 4 (BRD4) expression." (PMID 39198331, 2024). "LncRNA XIST silencing protects against sepsis-induced acute liver injury via inhibition of the BRD4 expression." (PMID 35309298, 2022). "The myeloid lineage-specific Brd4 conditional knockout mice (termed Brd4 CKO) are used to further investigate the pathological effects of BRD4 in sepsis." (PMID 33776776, 2021). "BRD4 has been shown to play a key role as a cofactor in promoting transcriptional activation of inflammatory genes, in sepsis as well as atherogenesis." (PMID 33257646, 2020). "For example, it is reported that lncRNA XIST silencing protects against sepsis-induced acute liver injury via inhibition of the BRD4 expression, and endoplasmic reticulum stress can suppress hepatic molecular identity through decommissioning of BRD4 super-enhancers in damaged liver." (PMID 33679744, 2021). "In the case of sepsis, according to the type of pathogen infection, the expression of BRD2, BRD3 or BRD4 shows heterozygosity and diversity in immune cells." (PMID 33776776, 2021).
bladder cancer (12 papers, 2018 to 2025). "Yan reported for the first time that BRD4 is upregulated in bladder cancer tissues, and its high expression is closely associated with a more malignant clinical feature and poor patient prognosis." (PMID 36733715, 2023). "Bromodomain-4 protein (BRD4) is upregulated in bladder cancer tissues and cells, where it enhances the migration and invasion of cancer cells by positively regulating the sonic hedgehog (SHH) signaling pathway." (PMID 40635786, 2025). "Recent studies have identified the BRD4 protein as the critical factor in regulation of cell proliferation and apoptosis in bladder cancer, and it shows promising potential for pharmacologic treatment against bladder cancer." (PMID 36733715, 2023). "It has been reported that BRD4 knockdown leads to cell cycle arrest, cell apoptosis and tumor growth inhibition in bladder cancer both in vitro and in vivo." (PMID 36733715, 2023). "Wu has recently reported that BRD4 can positively regulate EZH2 gene expression through upregulation of c-MYC and that the BRD4/c-MYC/EZH2 axis plays a vital role in the regulation of bladder cancer progression." (PMID 36733715, 2023). "They further conducted survival analysis and concluded that BRD4 expression predicted poor prognosis in bladder cancer patients." (PMID 35371325, 2022). "Studies have shown that c-Myc is enabled to act as a transcription factor for the progression of bladder cancer after BRD4 forms a complex with the c-Myc promoter." (PMID 34445958, 2021). "As an endogenous blocker, circNR3C1 binds to the BRD4 protein first, and then disconnects the formation of the BRD4/c-Myc complex, ending up inhibiting the progression of bladder cancer." (PMID 34445958, 2021). "Circular RNA circNR3C1 dissociates BRD4 from binding to the c-Myc promoter in bladder cancer cell lines and suppresses bladder cancer progression as an endogenous blocker of BRD4." (PMID 34540900, 2021). "BRD4 has been shown to be activated in bladder cancer, where it promotes tumor progression, BRD4 knockdown negatively regulated EZH2 transcription through downregulation of C-MYC and exerted anticancer effects." (PMID 32303673, 2020). "Recently, Wu revealed BRD4 as a novel promising target for pharmacologic treatment against bladder cancer and reported that BRD4 regulates proliferation and apoptosis of bladder cancer cells by positively regulating EZH2 transcription through upregulation of c-MYC." (PMID 36733715, 2023). "Moreover, the pharmacological effects of cisplatin (DDP), a chemotherapy agent used to inhibit tumor growth in vivo, are reduced by the overexpression of BRD4, suggesting that BRD4 could serve as a novel therapeutic target for bladder cancer." (PMID 40635786, 2025). "Furthermore, an exonic circular RNA (circNR3C1) which is generated from NR3C1 gene, interacts with bromodomain-containing protein 4 (BRD4) causing dissociation of BRD4/MYC complex and preventing MYC function as a transcription factor to inhibit bladder cancer progression." (PMID 39031286, 2024). "Additionally, BRD4 has been shown to regulate EZH2 expression in bladder cancer." (PMID 38001678, 2023). "However, for bladder cancer (BLCA), cervical squamous cell carcinoma (CESC), kidney renal clear cell carcinoma (KIRC), and uterine corpus endometrial carcinoma (UCEC), the expression of BRD4 in tissues from patients was not significantly higher than that in tissues from healthy subjects." (PMID 30988278, 2019).
breast tumor (11 papers, 2018 to 2022). "This suggests a potential link between BRD4-associated tumor progression and the inflammatory lymphocytic infiltrate in breast tumors." (PMID 30029633, 2018). "BRD4 was found to be significantly higher expressed in basal-like BCs compared to luminal breast tumours even within TNBC, suggesting a relevant role of BRD4 in BCs with basal-like phenotype." (PMID 35267409, 2022). "As a first step to characterize the effect of JQ1 on TNBC-specific SEs, ChIP-seq profiles for BRD4 in a panel of JQ1 or DMSO treated breast tumor lines were analyzed." (PMID 33854062, 2021). "The second SRB contains recurrent microdeletions (<50 kb) involving the 5′ end of BRD4 in ovarian (eight cases, P < 10−7) and breast tumours (six cases, P < 0.04)." (PMID 32025015, 2020). "Recent studies suggest that pharmacologic inhibition of BRD4, a required cofactor for YAP/TAZ transcriptional activity, blunts growth of YAP/TAZ-addicted breast tumors." (PMID 32960816, 2020). "The focal deletions in BRD4 overlap a prominent exon-1 H3K4me3 peak and intron-1 enhancer elements in HMEC (normal breast) and MCF-7 (breast tumour) cells, which suggests that these deletions disrupt regulatory elements." (PMID 32025015, 2020).
diffuse large B-cell lymphoma (11 papers, 2018 to 2025). "In diffuse large B cell lymphoma, approximately one-third of BRD4 protein localizes to super-enhancers which occupy ~1.6% of genes." (PMID 38135679, 2023). "The OCA-B oncogene is upregulated by BRD4-loaded super-enhancers that interact with POU2AF1 loci and cause the development of diffuse large B-cell lymphoma (DLBCL)." (PMID 37190100, 2023). "Treatment with four different BRD4 inhibitors reduces the expression of super-enhancer-associated oncogenes, such as MYC, E2F1, BCL6 and PAX5, and reduces diffuse large B cell lymphoma cell proliferation." (PMID 38135679, 2023). "POU2AF1 hypo-methylated probes span a known BRD4-regulated super-enhancer activated in Diffuse Large B Cell Lymphoma." (PMID 34793513, 2021). "Meanwhile, JQ1 is a prototype BRD4 inhibitor with proven therapeutic benefits in MM, AML, diffuse large B-cell lymphoma (DLBCL), prostate cancer, and breast cancer." (PMID 38225241, 2024).